RBM18 (RNA binding motif protein 18)
Synonyms: MGC2734
Tractability: PROTAC: ubiquitination databases record sites on it.
Gene: Protein-coding gene on chromosome 9 (122,237,622 to 122,264,855, reverse strand). Ensembl gene ENSG00000119446.
Subcellular location (Human Protein Atlas): Nucleoplasm; Cytokinetic bridge; Cytosol
Gene Ontology:
Molecular function: nucleic acid binding; RNA binding
Cellular component: cytosol; nucleoplasm
Genetic constraint (gnomAD): Loss-of-function variants: 13 observed, 21.49 expected, observed/expected ratio (o/e) 0.6, 90% interval 0.39 to 0.96. The upper end of that interval is the gene's LOEUF score, 0.96, which puts it in group 4 of 6, group 1 being the genes least tolerant of losing a copy. Missense variants: 128 observed, 182.05 expected, observed/expected ratio (o/e) 0.7, 90% interval 0.61 to 0.81. Synonymous variants: 60 observed, 70.03 expected, observed/expected ratio (o/e) 0.86, 90% interval 0.69 to 1.06.
Homologues: Orthologues: chimpanzee RBM18 (100% identical), macaque RBM18 (100% identical), guinea pig RBM18 (99% identical), mouse Rbm18 (99% identical), rat Rbm18 (99% identical), pig RBM18 (98% identical), dog RBM18 (86% identical), tropical clawed frog rbm18 (79% identical), rabbit RBM18 (75% identical), zebrafish rbm18 (69% identical), Drosophila melanogaster CG14414 (34% identical).